KEAP1 (kelch like ECH associated protein 1)
Diseases named in the same sentence as KEAP1 in open-access papers (continued):
Sharing a sentence is not in itself a finding about the gene and the disease.
tumor (continued). "In normal cells and tumor cells, the Keap1-Nrf2/ARE pathway comprises Nrf2 and its inhibitory protein Keap1 (Kelch-like ECH-associated protein 1) and ARE (antioxidant response element) is an important regulatory way to reduce ROS levels." (PMID 37305326, 2022). "Conversely, the study of a mouse model constructed with Keap1 knockout in the liver had showed smaller tumours." (PMID 36142252, 2022). "Collectively, it is inferable that Keap1 acts as a potent tumour promoter, and its major isoform Keap1α can prevent tumour development and malgrowth." (PMID 36142252, 2022). "NRF2/KEAP1 signaling commonly acts as cellular defensive machinery under oxidative stress, which is a vital factor correlated with neoplastic diseases." (PMID 35754474, 2022). "Of note, our data also showed that Keap1−/− xenograft mice developed fewer and smaller tumours than Keap1+/+ control mice, with a lower tumour frequency in nude mouse subcutaneous tumour transplantation experiments." (PMID 36142252, 2022). "Mechanistically, TRIM15 destabilized Keap1 via enhancing its ubiquitination and degradation, and accordingly prevented degradation of Nrf2 resulting in activation of Nrf2 pathway, enhanced tumor proliferation and metastasis." (PMID 35534896, 2022). "It should be noted that the effects of Keap1 deletion and subsequent activation of Nrf2 are differentially manifested in distinct tumour models, and thus these results are still controversial." (PMID 36142252, 2022). "On the other hand, HDAC3 also regulates KEAP1/NRF2 in tumor cells through modulating the expression of miR-200a as well." (PMID 35754474, 2022). "Overall, the results derived from human datasets and clinical samples strongly supported the possibility that UBR7 act as a tumor suppressor in HCC by regulating Keap1/Nrf2/Bach1/HK2 axis." (PMID 36419136, 2022). "This article reviews the role of PD-L1 expression, tumour mutational burden (TMB), smoking history, STK11/KEAP1 mutations and the gut microbiome as predictive markers for immunotherapy." (PMID 35200543, 2022). "Our study, therefore, attributes a highly tumor-relevant function to Keap1 as it stands to play during the earliest stages of locally growing tumors, during which the cellular burden of mutations is low." (PMID 36321803, 2022). "Among the significantly enriched guide RNAs were known tumor suppressors KEAP1 and FBXW7 as well as several members of the Cullin 5 (CUL5)-RING E3 ligase (CRL5) complex, a previously undescribed mechanism of resistance." (PMID 34944063, 2021). "Studies on bladder cancer cells present evidence that p62 promotes tumor cell growth by activating Keap1-Nrf2 signaling." (PMID 34073079, 2021). "To further clarify the relationship between tumor size and the expression of NRF2 or KEAP1, we constructed the relationship between gene expression and tumor size." (PMID 34862368, 2021). "Correspondingly, reduced tumor growth has been reported in Keap1 mutant NSCLC xenograft after G6pd and Tkt silencing." (PMID 34440648, 2021). "Keap1 knockdown promotes tumor cell growth, proliferation, invasion, metastasis and chemotherapy resistance in LUAD." (PMID 34466284, 2021). "Previous studies suggest that loss of KEAP1 function may lead to the nuclear translocation of Nrf2 and subsequent increased expression of cellular antioxidants and xenobiotic detoxification enzymes, which may be the major resistance mechanism of tumor cells against chemotherapeutic drugs." (PMID 34399705, 2021). "In tumor condition, the decrease of the circKEAP1 resulted in the evaluation of miR-141-3p, which in turn suppress the protein level of KEAP1 and increase the NRF2 level." (PMID 34136401, 2021).
tumor (continued). "The inactivating mutations in KEAP1 and LKB1, as well as the activation of the YAP1 and/or RSK-mTOR pathway, contribute to mutant KRAS independency in tumor cells, potentially causing therapeutic resistance to KRAS inhibitors." (PMID 34885068, 2021). "Keap1 is a major negative regulator of Nrf2, which has been shown to inhibit the proliferation and cisplatin resistance of tumor cells." (PMID 34466284, 2021). "It was well known that NRF2 acted as an oncogene, and its principal repressor KEAP1 acted as a tumor suppressor." (PMID 34226519, 2021). "In general, the differences in metabolites between WT and Keap1-KD were greater than the differences between WT and Nrf2-KO genotypes in both tumor and peri-tumoral tissues." (PMID 34526660, 2021). "According to their study, SLC27A5 deficiency promotes tumor proliferation and chemoresistance by increasing 4-HNE level and consequently activating KEAP1/NRF2/TXNRD1 pathway." (PMID 33731144, 2021). "Here, we show that the differences in metabolites between tumor and peri-tumoral colon tissues of Gstp−/−: ApcMin/+ mice are enhanced by Keap1 knockdown." (PMID 34526660, 2021). "The GSEA results manifested that KEAP1/NFE2L2/CUL3 Mut group patients have a complex ROS mechanism that affects tumor development." (PMID 34617407, 2021). "Then, somatic mutations in Kelch/IVR domain of KEAP1 were detected in both human NSCLC cell lines and clinical NSCLC patients’ tumor samples." (PMID 33808001, 2021). "Consistent with this, it was shown that glutaminase inhibitor CB-839 suppresses tumor growth of KEAP1-mutant cell line- or patient-derived xenografts (PDXs) much more potently than that of KEAP1-WT counterparts." (PMID 33000412, 2021). "CD38 KO and MU tumor cells showed a higher expression of KEAP1 than that of WT and OE cells, while NRF2 was on the contrary." (PMID 34226519, 2021). "To assess the role of Keap1 in tumor EMT, we performed western blot analysis of EMT marker proteins." (PMID 34466284, 2021). "The overexpression of Nrf2 and the knockout of Keap1 can promote the proliferation and migration of tumor cells by upregulating the activity of xCT, thus changing the tumor microenvironment and inhibiting ferroptosis." (PMID 34869322, 2021). "Cases with mutations in KEAP1 and FAT1 tended to have higher TMB and neoantigen loads but a lower expression of immune-related genes and tumor-infiltrating CD8+ cells than cases with wild-type genes." (PMID 33808631, 2021). "In conclusion, this study confirmed the interaction between the Keap1–Nrf2 axis and Nestin and that Nestin can mediate antioxidant responses and maintain tumor phenotypes in GC." (PMID 34772403, 2021). "It is important to note that the chosen tumor cell lines in this study differ regarding the NRF2-repressor molecule KEAP1." (PMID 33441543, 2021). "The mutations of several genes in different tumor settings such as NRF2 (nuclear factor erythroid 2-related factor 2), KEAP1 (kelch-like ECH-associated protein 1), and KRAS, have been identified as radiosensitising or radioresistant factors." (PMID 36046142, 2021). "This study demonstrates the potential effect of KEAP1 mutation on tumor immune milieu of LUAD subtype of NSCLC patients, highlighting the potential efficacies of the immunotherapy treatment using PD‐L1 blockers in KEAP1‐wild type LUADs." (PMID 34328274, 2021). "As a tumor suppressor frequently lost or mutated in NSCLC, KEAP1 profiles as a possible target for AAV9-mediated gene replacement therapy once the technology has been refined." (PMID 34944063, 2021). "The involvement of the Keap1–Nrf2 axis in the Nestin-modulated antioxidant response and tumor phenotypes (proliferation and metastasis) of GC was also elucidated." (PMID 34772403, 2021).
tumor (continued). "In this tumor type, the inactivation of KEAP1 results in a constitutive activation of NRF2 and decrease in ROS, promoting tumor aggressiveness, metastasis and resistance to radiotherapy and oxidative stress." (PMID 34141616, 2021). "Nuclear accumulation of NRF2 and low expression of KEAP1 correlated with tumor aggressiveness, although the expected phenotypic outcomes were not necessarily consistent in cases of somatic mutation in KEAP1 vs. NFE2L2." (PMID 32938017, 2020). "Here, the authors show that TRIM25 is induced during ER stress and promotes tumour cell survival by targeting Keap1 for degradation, leading to Nrf2 activation." (PMID 31953436, 2020). "Specifically, our results demonstrate that the loss of KEAP1 in human cells leads to a significant increase in NQO1 expression, which is known to facilitate tumor growth through HIF-1 binding." (PMID 32424161, 2020). "The locations of the differentially-methylated CpG sites between KEAP1-mutated and wild-type LUAD tumor samples varied among promoter, 5′UTR, 1st exon, and gene body." (PMID 32327612, 2020). "Mutations in NFE2L2, that specifically cluster to regions of the gene encoding amino acids in NRF2 that bind KEAP1, have been documented in early preneoplastic liver lesions and HCC tumour samples." (PMID 33276631, 2020). "Although the Keap1-Nrf2 pathway represents a powerful cell defense mechanism against a variety of toxic insults, its role in acute or chronic liver damage and tumor development is not completely understood." (PMID 33053665, 2020). "Mutations in KEAP1 and CUL3 genes are mutually exclusive with the one in the NFE2L2 gene present in 6.6% of ccRCCs; indeed 10.4% of the tumor analyzed presented a deletion in the CUL3 locus 2q36." (PMID 33233657, 2020). "These lines of evidence suggest that constitutive activation of the KEAP1/NRF2 signaling pathway can permit tumor cells to withstand a harsh oxidative external microenvironment, delineating the “double-edged sword” aspect of the KEAP1/NRF2 signaling pathway." (PMID 32823937, 2020). "Then, we investigated the association between the clusters and clinical characteristics, and sex, tumor stage, smoking history, STK11 mutation, and KEAP1 mutation were significantly (P‐value < 0.05) associated with clusters." (PMID 32688456, 2020). "NRF2 activation confers Kras/Lkb1/Keap1 (KLK) mutant tumor cells with greater resistance to oxidative insults." (PMID 33299528, 2020). "This is demonstrated by the fact that the genetic inactivation of p62 in mice fully impaired tumor formation, likely due to the restauration of the Keap1-Nrf2 binding and subsequent Nrf2 inactivation." (PMID 33053665, 2020). "For instance, the tumor-specific hypermethylation of the KEAP1 promoter region was suggested as a specific feature of a clear cell renal carcinoma." (PMID 33228209, 2020). "Activation of the TrkB-mediated PI3K/AKT pathway decreases the expression of Runx3 and Keap1 tumor suppressors." (PMID 32340410, 2020). "Other co-alterations that have a potential impact on tumor biology include KEAP1 (4%) and combined CDKN2A/CDKN2B (4%)." (PMID 32295619, 2020). "KEAP1 deletion contributes to tumor aggressiveness, metastasis, and increases radioresistance in LUSC." (PMID 32723974, 2020). "In agreement with our data, RB1 mutations occurs in 35% of LCNECs as well as typical NSCLC mutations such as KEAP1 and STK11 only occur in this tumor variants compared to both NETs and SCLCs (p < 0.0001)." (PMID 32987854, 2020). "In previous studies, loss of KEAP1 function promoted tumour growth, suggesting that KEAP1 is a tumour suppressor gene." (PMID 31659154, 2019). "NRF2‐activating or KEAP1‐inactivating mutations 65, or oncogene‐mediated transcriptional induction of NRF2 7, contribute to NRF2 activation in diverse tumor types." (PMID 31668005, 2019). "We demonstrate that KEAP1 is a potent tumor suppressor that promotes malignancy through a metabolic dependency on the PPP." (PMID 31519898, 2019).
tumor (continued). "Having established the unique nature of the bronchiolar-induced immune microenvironment in KEAP1-mutant KRAS-driven LUAD, we sought to identify the underlying mechanisms of tumor progression in this genetic subtype." (PMID 31519898, 2019). "It was found that patients with decreased Keap1 expression exhibited a worse prognosis, which was consistent with previous study demonstrating that Keap1 functions as a tumor suppressor." (PMID 30811526, 2019). "In line with mouse cell line and spontaneous tumor studies, KEAP1-mutant cell lines displayed increased sensitivity to PPP inhibition (IC50 KEAP1MUT 9.9 ± 6.4 μM vs. KEAP1WT 44.5 ± 7.9 μM)." (PMID 31519898, 2019). "The adenovirus ZD55-IL-24 promoted the association between NRF2 and KEAP1 and attenuated the ARE-dependent gene transcription by activating the p38/JNK but inhibiting the ERK pathways in A549, leading to tumor-specific apoptosis." (PMID 31097977, 2019). "Further, glutathione biosynthesis is required for tumor initiation and progression, and numerous oncogenic alterations promote glutathione biosynthesis by activating the Keap1/Nrf2 pathway." (PMID 31096630, 2019). "KEAP1 methylation levels measured in the tumor cell lines ranged as follows: 0–228 (SCLC), 0–78.8 (Carcinoids), 0–492 (ADC, SqCC, LCC)." (PMID 31159323, 2019). "Frequent LOH was observed in at 19p13.2, thus confirming the role of KEAP1 as a tumor suppressor gene." (PMID 31126053, 2019). "KEAP1 deregulation by CpG hypermethylation appears complex upon investigation; it was studied in large tumor cohorts, but less is known about the details of CpG methylation density pattern." (PMID 31159323, 2019). "In line with the antioxidant enzyme expression, in the present study tumor hosts showed increased Nrf2/Keap1 ratio, likely induced by muscle oxidative stress." (PMID 30823492, 2019). "These 12 NRF2 activated tumor cases consisted of 6 cases (3 LUSC and 3 LUAD) with NRF2 mutations and 6 cases (3 LUSC and 3 LUAD) with KEAP1 mutations." (PMID 30150714, 2018). "By reviewing the list of genes without impact like ERBB3, CASP8, RAF1 and KRAS (FaDu) as well as KEAP1, KRAS, RAF1 and FANCD2 (SAS), one finds tumor drivers ranked among the top 100 mutated genes in HNSCC." (PMID 29719593, 2018). "In this tumor, miR-432-3p overexpression correlates with a downregulation of the KEAP1 expression, thus inducing a decrease in the sensitivity of tumor cells to cisplatin and other chemotherapy drugs." (PMID 29643973, 2018). "In silico analysis and in vitro studies on different sets of tumor cell lines recently provided more additional insights into the role of KEAP1/NRF2 axis modulation by miRNAs." (PMID 29643973, 2018). "Altered levels of both glutamine and glutamate in the tumor microenvironment of KEAP1 mutant tumors can effect cell signaling and regulate cell growth and proliferation pathways." (PMID 28967864, 2017). "KEAP1 mRNA levels were found to be elevated for both tumor mtDNA depleted lines, suggesting a role for this pathway in the antioxidant response." (PMID 28771582, 2017). "The ubiquitinated structure and phosphorylated p62 and Keap1 complexes are autophagically degraded, leading to the elimination of cytotoxic components, thereby protecting the tumor cells." (PMID 28941211, 2017). "A tumor-specific DNA methylation of the KEAP1 gene promoter region was found as a specific feature of the ccRCC subtype (18/37, 48.6%) and a direct correlation with mRNA levels was confirmed by in vitro 5-azacytidine treatment." (PMID 28061437, 2017). "Although genetic alterations of the Keap1/Nrf2 pathway were reported only in a small fraction of ccRCCs (6.6%), tumor-specific DNA methylation of the KEAP1 gene promoter has been detected in 48.6% of the tumors." (PMID 28812986, 2017). "KEAP1 mRNA levels were elevated for both tumor ρ0 cell lines at baseline and after irradiation compared to their parentals." (PMID 28771582, 2017).
tumor (continued). "By using protein structures, we identified potentially inactivating mutational clusters in critical regions of several tumor suppressors including PTEN, CDH1, and KEAP1." (PMID 28115009, 2017). "Pre-NACT core needle biopsies and postoperative tumor samples were immunohistochemically stained for nuclear factor erythroid 2-related factor 2 (Nrf2), Kelch-like ECH-associated protein 1 (Keap1), thioredoxin (Trx), and peroxiredoxin I (Prx I)." (PMID 29348788, 2017). "A clear association was observed between the hypermethylation of CpGs located in the KEAP1 promoter and an increased ccRCC tumor grading and staging, further supporting their biological relevance." (PMID 28061437, 2017). "The discriminatory power of the KEAP1 QMSP assay was assessed by estimating the area under the ROC curve using paired normal renal tissues distant from tumor and ccRCCs." (PMID 28061437, 2017). "This study determined the mRNA levels of Nrf2, Keap1, Bach1, and Hmox1, both in the tumor and in normal tissues, to investigate their correlations in CRC." (PMID 27999449, 2016). "S351-phosphorylated p62 and Keap1 accumulate, and form aggregates, in tumours that are defective for autophagy, resulting in persistent activation of Nrf2 (refs 9, 16, 17)." (PMID 27345495, 2016). "It has been recently demonstrated by in vitro analysis that the methylation status of KEAP1 can also predict the tumor cells sensitivity to radiation." (PMID 27847554, 2016). "The tumor had higher Keap1/Nrf2 and Bach1/Nrf2 but lower Homx1/Nrf2 mRNA ratios compared to the normal tissue." (PMID 27999449, 2016). "As a sensitive receptor for oxidative stress, Nrf2/Keap1 signaling pathway played a crucial role in preventing cells from apoptosis, stress, inflammation, and tumor." (PMID 26649146, 2016). "In the tumor tissue with undetectable Bach1 mRNA expression, the correlation between the mRNA levels of Keap1 and Hmox1 was the only one that remained significant." (PMID 27999449, 2016). "Aggregate structures positive for phosphorylated p62 and Keap1 were present in tumour regions in HCV-positive HCC patients, implying robust activation of Nrf2." (PMID 27345495, 2016). "Hua KT and his colleagues demonstrated that Keap1 functions as a suppressor of tumor metastasis by targeting the Nrf2/S100P pathway in non‐small‐cell lung cancer cells." (PMID 27650414, 2016). "Apart from conferring the resistance of tumor cells to therapy, Keap1–Nrf2 pathway also promotes proliferation." (PMID 27200299, 2016). "Keap1 staining correlated with tumor stage (FIGO stage I B to IIB), lymph node status (N0 to N1), and pathological grade (GI to GIII)." (PMID 26247201, 2015). "We evaluated levels of KEAP1 methylation in normal tissues and tumor specimens using a Sequenom MassARRAY platform." (PMID 26247201, 2015). "It must be kept in mind that chemopreventive agents including various phytochemicals can induce chemoresistance and tumor progression by activating the Keap1-Nrf2 pathway." (PMID 25699252, 2015). "We found that in tumor cell lines with low or mutant KEAP1, and in Keap1-/- murine embryonic fibroblasts, multiple KEAP1 targets including NRF2, IKKβ, and BCL2 were elevated." (PMID 26301506, 2015). "No known oncogenes were found mutated, but four of the seven patients (GIST_150, _174, _124 and _188) showed deleterious mutations in two candidates (KEAP1 and LATS2) and in three well-known tumor suppressors (CDKN2A, CDKN1B and PTEN)." (PMID 26544626, 2015). "Further detailed mechanistic studies, addressing how accumulated metabolites in the intermediary metabolism cooperate with the Keap1/Nrf2 pathway to assist the tumor development will be an interesting theme of future investigations." (PMID 25014534, 2014).